INS (insulin)
Diseases named in the same sentence as INS in open-access papers (continued):
Sharing a sentence is not in itself a finding about the gene and the disease.
Insulin resistance (continued). "Second, the lack of data reflecting islet β cell function such as fasting insulin and C-peptide levels resulted in the defect of the putative association between CFH and insulin resistance during pregnancy." (PMID 34404360, 2021). "This study aimed to assess the importance of the insulin level and insulin resistance in PCOS patients based on obesity." (PMID 33750349, 2021). "Another possible explanation for the lower predictive value of insulin secretion compared to insulin resistance is the changing nature of insulin secretion in the progression of early dysglycemia." (PMID 34206745, 2021). "Pro-inflammatory factors, like IL-6, TNF-α, MCP-1, also aggravated glucose dysregulation and inhibited normal insulin signaling, resulting in insulin resistance (IR)." (PMID 33778016, 2021). "Increased insulin resistance (IR); decreased glucose effectiveness (GE); and both first-and second phase of insulin secretion (FPIS, SPIS) have always been important factors for the development of type 2 diabetes." (PMID 34106595, 2021). "Type 2 diabetes (T2D) is characterized by fasting hyperglycemia resulted from the inadequate secretion of the glucose-lowering hormone insulin and/or insulin resistance (IR)." (PMID 34884651, 2021). "As a result, the cellular pathway involving insulin secretion will be stimulated, reducing the possibility of insulin resistance, acting as an anti-diabetic agent." (PMID 34639164, 2021). "Fibroblast growth factor-19 (FGF19) is a hormone-like enterokine which can reduce the blood glucose of insulin resistance model mice (ob/ob mice and high-fat diet mice) and enhance insulin sensitivity." (PMID 34307371, 2021). "T2DM has a basis in insulin resistance, although a reduction in insulin secretory capacity is observed over time." (PMID 34073737, 2021). "Treatment with MLT significantly ameliorated hyperglycemia and the reduction of insulin levels, blocked the glycosylation of hemoglobin and improved insulin resistance in T2DM rats." (PMID 33748504, 2021). "Insulin resistance mainly occurs in fat, muscle, and liver cell populations, which use insulin to facilitate glucose uptake." (PMID 34959658, 2021). "In genetically predisposed individuals, however, β-cells have limited capacity to compensate for increasing insulin demand resulting from insulin resistance, hyperglycemia and hyperlipidemia." (PMID 34943836, 2021). "Insulin resistance refers to the disruption of insulin section of pancreatic β-cells and the deceased sensitivity of organs in glucose utilization." (PMID 35111696, 2021). "Blood glucose and insulin levels as well as level of insulin resistance indices during the control (CON) and Nordic walking (NW) stages." (PMID 34539448, 2021). "Cluster 1 children (with the mostly sedentary state) exhibited higher insulin, Homeostatic Model Assessment for Insulin Resistance, and triglyceride levels." (PMID 34976884, 2021). "Herein, we show that insulin resistance in GK rats is significantly reduced by luteolin treatment, highlighting the major role of this flavone in controlling insulin sensitivity." (PMID 34948468, 2021). "In the setting of insulin resistance and hyperglycemia, high insulin secretory demand is placed on the β cell." (PMID 34822454, 2021). "Insulin resistance is defined as a decrease in insulin sensitivity in the major insulin target organs such as adipose tissue, liver, and muscle." (PMID 34650665, 2021). "Attenuation of TNFα/IL-1β/CCL2-mediated inflammation in metabolic organs has been shown to improve insulin resistance, consistent with the observed reduction of fasting insulin and HOMA-IR in KrO-treated mice." (PMID 34444996, 2021). "Reduced TMAO levels in FMO3 knockdown mice reversed insulin resistance as measured by blood glucose and insulin levels." (PMID 34445033, 2021). "Insulin resistance is a pathological condition with impaired sensitivity to insulin in target tissues." (PMID 34299261, 2021).
Insulin resistance (continued). "Although impaired glucose metabolism and insulin resistance have been described in Gitelman patients, the minor changes in plasma insulin levels make it unlikely that insulin is responsible for hypomagnesaemia in Na+ wasting disorders." (PMID 32603001, 2021). "This local inflammatory milieu is an important etiological factor of the development of insulin resistance, dysfunction of insulin secretion and hyperglycemia." (PMID 34384426, 2021). "Although type 2 diabetes has been accurately described as a disease of insulin resistance, a large number of treatment centers around giving the patient more insulin." (PMID 33921979, 2021). "TNFα directly affects insulin signalling and, thus, has a role in the development of insulin resistance and obesity." (PMID 34572059, 2021). "Adiponectin also increases insulin sensitivity in muscles and liver through the AMPK pathway and improve insulin resistance as an endogenous insulin sensitizer." (PMID 33842335, 2021). "In response, β-cells proliferate and synthesize more insulin as a mechanism to counteract insulin resistance and favor euglycemia." (PMID 34360849, 2021). "The results also imply the effect of insulin of increasing BP independently of changes in glycemia and insulin resistance." (PMID 34579668, 2021). "Type 2 diabetes mellitus (T2DM) is a chronic multifactorial hyperglycaemic disease characterised by insulin resistance and impaired insulin secretion." (PMID 33390804, 2021). "Our study results suggest that, although there is no exact link between laminin and non-alcoholic hepatosteatosis, serum laminin levels are lower in patients with insulin resistance by regulating the insulin effect through integrins." (PMID 34092237, 2021). "Insulin resistance (IR) typically refers to the condition that target tissues of insulin show decreased sensitivity to insulin-related metabolic actions." (PMID 34589530, 2021). "We also noticed that baicalin ameliorated insulin resistance by observing the decrease in the insulin level and HOMA-IR." (PMID 34135978, 2021). "Many reports have shown that adiponectin leads to enhanced insulin action in vitro and in vivo, strongly suggesting its protective role against insulin resistance." (PMID 35050148, 2021). "In the univariate analysis, the highest correlations for PLWH subjects were observed for triglycerides, insulin levels and insulin resistance with a p-value <0.0001 for these three variables." (PMID 34019585, 2021). "An elevated RQ at baseline was significantly associated with increased visceral adipose tissue, hepatic fat, higher levels of insulin and homeostatic insulin resistance." (PMID 34209600, 2021). "Our data illustrated the repression of miR-143-3p protects against insulin resistance in MetS as well as obesity mice models by activating the insulin signaling pathway." (PMID 34485272, 2021). "Observed also in mice fed a HFD are increased basal glucose and insulin levels, glucose intolerance, and insulin resistance." (PMID 33503814, 2021). "For example, at the same insulin level, patients with insulin resistance have less cortical activation compared with normal individuals." (PMID 34531719, 2021). "The serum insulin level was reduced by approximately 35%, the insulin resistance index was reduced by more than 66%." (PMID 34439921, 2021). "Studies show that TNF-α incubation inhibits insulin-stimulated glucose uptake and leads to insulin resistance in adipocyte cell lines." (PMID 34717724, 2021). "Galangin (50 mg/kg) and metformin corrected the insulin resistance by reducing the levels of fasting glucose, fasting insulin, and the HOMA-IR index in MS rats (p < 0.05)." (PMID 34066039, 2021). "Insulin resistance (IR) is defined as a lower-than-expected response to insulin action from target tissues, leading to the development of type 2 diabetes through the impairment of both glucose and lipid metabolism." (PMID 33800465, 2021).
Insulin resistance (continued). "Oxidative stress induces insulin resistance by disturbing the insulin signaling pathway, affecting regulation at the level of adipokines and favoring some of the mentioned serine–threonine kinases pathways." (PMID 34829598, 2021). "Due to the joint occurrence of insulin resistance and ectopic fat accumulation, the majority of studies focus on the immediate effect of lipids on the constituents of the insulin signaling pathway." (PMID 33815291, 2021). "At both the 75 mg and 300 mg doses, significant improvements in a marker of insulin sensitivity (i.e., Homeostatic Model Assessment of Insulin Resistance) were observed." (PMID 33621267, 2021). "An in vitro study has demonstrated that glutamine can enhance glucose-stimulated insulin secretion, contributing to worsening insulin resistance of patients with multiple trauma." (PMID 33865313, 2021). "Decreases in fasting blood glucose level, TG in the liver, TC, LDL, leptin, insulin, and insulin resistance were also noted." (PMID 33435282, 2021). "Adipose tissue dysfunction is considered a hallmark of type 2 diabetes and a major contributor to the development of insulin resistance, which in addition to β-cell dysfunction and impaired insulin secretion, forms the cornerstones of type 2 diabetes biology." (PMID 34426590, 2021). "Altogether, it is clear that oxidative stress is an important factor in brain insulin resistance that can influence and be influenced by the lipid content and inflammatory and metabolic states of the brain during insulin-resistant conditions." (PMID 33845179, 2021). "Treatment of mHypoE-46 neurons with high levels of insulin for 24 h identified miR-1983 as a candidate that is induced with insulin resistance in hypothalamic neurons." (PMID 34831343, 2021). "Indices reflecting insulin resistance including 2-h 75 g GTT insulin, FGIR, HOMA-IR were markedly higher in NAFLD group." (PMID 33782517, 2021). "New analyses have demonstrated that berberine has numerous pharmacological benefits, such as lowering blood glucose, antioxidant activity, blood lipid regulation, reduced inflammation, and elevated insulin sensitivity, thus improving insulin resistance." (PMID 34684678, 2021). "Hepatic lipids tend to further exacerbate insulin resistance by interfering with insulin signaling, thus perpetuating the vicious cycle." (PMID 34141709, 2021). "Hyperinsulinemia is described as elevated concentrations of circulating insulin in the blood due to insulin resistance and is common in obesity and the early stages of T2D." (PMID 34835407, 2021). "Some studies have found that brain had the ability to secrete insulin locally, and insulin resistance in the Central Nervous System is also considered to be directly related to neurodegeneration, which also involves autophagy inhibition." (PMID 34671214, 2021). "The prevailing therapeutic approaches to type 2 diabetes have focused on drugs that either improve insulin resistance or increase insulin secretion and decrease glucagon secretion." (PMID 34882233, 2021). "Our study did not reveal a significant association between bacteria counts, fasting glucose, fasting insulin levels, and the index of insulin resistance HOMA-IR." (PMID 32779013, 2021). "Ever since the study of the impaired responsiveness to insulin of the diabetics opened by Berson and Yalow in the 1960s, insulin resistance has been proposed, investigated, demonstrated, and concluded as the initial defect in T2D." (PMID 34603195, 2021). "T2DM is a multifactorial chronic disease characterised by hyperglycaemia, originating from reduced sensitivity of target tissues to insulin (insulin resistance), and other metabolic dysfunctions." (PMID 34677434, 2021). "Oral glucose and insulin tolerance tests, immunohistochemical and immunofluorescent analyses manifested that 122 attenuated insulin resistance and alleviated liver injury in HFD-induced mice as an ideal natural product in NAFLD." (PMID 35069197, 2021).
Insulin resistance (continued). "Effects on glucose kinetics and insulin sensitivity are inconsistent, but minor degrees of insulin resistance have also been reported." (PMID 35173682, 2021). "Kaempferol treatment in HFD- and STZ-treated rats reduced circulating blood glucose, insulin levels and insulin resistance." (PMID 34970150, 2021). "Further studies are warranted investigating parameters more directly involved in the proposed pathways, such as insulin and insulin resistance." (PMID 34544031, 2021). "To further investigate the effects of MWE on glucose uptake in insulin resistance, we used insulin-resistant cells." (PMID 33800074, 2021). "CA given to chronic restraint stress-induced insulin-resistance mice showed to reduce fasting blood sugar, systemic inflammation, and oxidative stress, and improve insulin sensitivity." (PMID 34576959, 2021). "Blood-based biomarkers of healthy aging included those associated with glycemic control (glycated hemoglobin, fasting plasma insulin and glucose, and homeostatic model assessment of insulin resistance)." (PMID 33983131, 2021). "Hyperinsulinemia can lead to insulin resistance by downregulating the mediators of the insulin signaling pathway." (PMID 34358068, 2021). "Insulin resistance is a condition in which there is a reduced response of organs to insulin actions, manifested by mild hyperglycemia (less than 125 mg/dL) and hyperinsulinemia in fasting and postprandial states." (PMID 34220716, 2021). "UA causes reduction in endothelial nitric oxide (NO) level, the key mediator of insulin action, which in turn disturbs blood flow and glucose uptake in skeletal muscles leading to insulin resistance and development of metabolic syndrome (MS)." (PMID 35008629, 2021). "From our findings, during insulin resistance, the secretion of these insulin signaling factors was sub-optimal." (PMID 33953863, 2021). "Its onset and progression are multifactorial but largely due to the development of systemic insulin resistance and insufficient insulin secretion 1-3." (PMID 33456576, 2021). "Insulin resistance, an important mechanism for the onset of type 2 diabetes, is manifested by the decreased sensitivity of peripheral tissues and organs to insulin." (PMID 33824679, 2021). "An alternative paradigm maintains that insulin hypersecretion by beta-cells is the primary defect, resulting in hyperinsulinemia which drives peripheral insulin resistance." (PMID 34659123, 2021). "Consistent with their insulin resistance, Sham-obese rats had the highest insulin levels among the three groups during the OGTT." (PMID 33535876, 2021). "Other studies have also shown that LRGT enhances insulin sensitivity and improves insulin resistance." (PMID 34975451, 2021). "Insulin dysregulation (ID) in horses is defined as any combination of fasting hyperinsulinemia, postprandial hyperinsulinemia or insulin resistance (IR)." (PMID 33588833, 2021). "As expected, baseline LP-IR was moderately correlated with baseline HOMA-IR, insulin sensitivity index, the reciprocal of insulin sensitivity index (i.e., 1/insulin sensitivity index as a proxy of insulin resistance), and Matsuda index." (PMID 33613319, 2021). "This is the first study that has assessed insulin resistance according to daily insulin requirements and evaluated the effects of exogenous insulin on cognitive functions." (PMID 34577866, 2021). "It is characterized by decline in insulin-producing β-cells, progressive peripheral insulin resistance and increased hepatic glucose production." (PMID 33802371, 2021). "One study showed that in human adipocytes, SFRP5 impairs insulin sensitivity, whereas associations between blood concentration of SFRP5 and homoeostasis model assessment of insulin resistance (HOMA-IR) vary between studies." (PMID 34184187, 2021).
Insulin resistance (continued). "Compared with baseline, BCSs experienced significant reductions in most of the metabolic and inflammatory parameters analyzed, including those related to insulin resistance (i.e., glycemia, insulin, and HOMA-IR) and inflammation (hs-CRP)." (PMID 34204528, 2021). "Based on screening assays, most potent concentration of extracts was selected to further testing with HepG2 cells treated with high concentrations of insulin and glucose as a model of insulin resistance." (PMID 34034759, 2021). "Group III (OVX control group) showed metabolic dysfunction (increased BMI, insulin level, and insulin resistance)." (PMID 33997010, 2021). "In summary, the number of studies examining the relationship between insulin resistance, insulin treatment, and cognitive functions is increasing, as the need for them is high, since the mechanisms and results remain inconsistent." (PMID 34577866, 2021). "Both are major contributors to insulin resistance, beta-cell dysfunction, impaired insulin secretion, and ectopic fat deposits." (PMID 34950104, 2021). "Alternate day fasting also increased SIRT1 levels in the liver of diabetic mice and reduced insulin resistance, inflammation, obesity and prolonging of insulin signaling." (PMID 33806509, 2021). "Evidence suggests that saturated fatty acids impair insulin secretion and induce insulin resistance via Src signaling in T2D." (PMID 34360006, 2021). "It is well established that hepatic, adipose, and muscle tissue insulin resistance and decreased pancreatic insulin production result from hyperglycemia brought about by excessive liver gluconeogenesis, which are all predictors of both T2D and NAFLD." (PMID 34497507, 2021). "It suppressed insulin resistance and enhanced insulin sensitivity and increased plasma LXA4 and BDNF levels and pancreas, brain, liver, and intestine BDNF concentrations." (PMID 33546300, 2021). "Increased FAK levels were found to increase glucose uptake and insulin sensitivity through insulin receptor Glut-4 translocation and FAK deficiency was associated with increased insulin resistance and TG levels." (PMID 34092237, 2021). "Kinases such as AMP-activated protein kinase (AMPK), Ikβ kinase (IKK), protein kinase C (PKC), and mitogen-activated protein kinases (MAPKs) play important roles in the development of insulin sensitivity and insulin resistance." (PMID 34445786, 2021). "Many studies in insulin-target tissues implicate defects in autophagy as potential contributors to the development of insulin resistance." (PMID 34336862, 2021). "In insulin resistance states, insulin-stimulated glucose disposal in the skeletal muscle is markedly impaired." (PMID 33708999, 2021). "Insulin resistance is characterized by the impairment of insulin action, resulting in persistent hyperglycemia and increased insulin production, e.g., hyperinsulinemia, frequently observed in children with obesity." (PMID 34436493, 2021). "The IRS-1/PI3K/Akt/Glut4 signaling pathway is a classical insulin signaling pathway that plays an influential role in alleviating diabetes-induced insulin resistance." (PMID 34691353, 2021). "Our present findings clearly show that Stevioside attenuates high fat diet-induced insulin resistance and improves glycemic control in diabetic gastrocnemius muscle by facilitating the expression of insulin signaling molecules and GLUT4." (PMID 34946771, 2021). "Because we observed important changes in glucose tolerance, we then studied the circulating levels of hormones such as GIP and insulin involved in inflammation and insulin resistance." (PMID 35010897, 2021). "The reduced response of peripheral target tissues to insulin action leads to insulin resistance (IR), a condition that is characterized by a compensatory increase of circulating insulin levels to maintain euglycemia." (PMID 34681797, 2021). "Improvement of insulin resistance in the experimental group is supported by post-intervention decreases of insulin/glucose ratio and HOMAR-IR." (PMID 34204042, 2021).